CDC37L1 (cell division cycle 37 like 1, HSP90 cochaperone)
Description:
Co-chaperone that binds to numerous proteins and promotes their interaction with Hsp70 and Hsp90.
Synonyms: CDC37B; HARC; FLJ20639
Tractability: Antibody: its Gene Ontology location is reachable by antibodies, with high confidence. PROTAC: ubiquitination databases record sites on it; its protein half-life has been measured.
Gene: Protein-coding gene on chromosome 9 (4,679,559 to 4,708,399, forward strand). Ensembl gene ENSG00000106993.
Subcellular location: Cytoplasm
Subcellular location (Human Protein Atlas): Cytosol
Pathways (Reactome):
Hemostasis: Platelet degranulation
Gene Ontology:
Molecular function: protein binding; heat shock protein binding; protein-folding chaperone binding
Biological process: protein folding; protein stabilization
Cellular component: cytosol; cytoplasm; extracellular region; platelet dense granule lumen
Genetic constraint (gnomAD): Loss-of-function variants: 14 observed, 17.68 expected, observed/expected ratio (o/e) 0.79, 90% interval 0.52 to 1.24. The upper end of that interval is the gene's LOEUF score, 1.24, which puts it in group 5 of 6, group 1 being the genes least tolerant of losing a copy. Missense variants: 214 observed, 196.8 expected, observed/expected ratio (o/e) 1.09, 90% interval 0.97 to 1.22. Synonymous variants: 76 observed, 73.04 expected, observed/expected ratio (o/e) 1.04, 90% interval 0.86 to 1.26.
Homologues: Orthologues: chimpanzee CDC37L1 (99% identical), macaque CDC37L1 (99% identical), dog CDC37L1 (95% identical), guinea pig CDC37L1 (93% identical), rabbit CDC37L1 (89% identical), mouse Cdc37l1 (89% identical), pig CDC37L1 (87% identical), rat Cdc37l1 (83% identical), tropical clawed frog cdc37l1 (55% identical), zebrafish cdc37l1 (44% identical), Drosophila melanogaster Cdc37 (27% identical), Caenorhabditis elegans cdc-37 (20% identical), and 1 more. Paralogues in human: CDC37 (38% identical).
Diseases named in the same sentence as CDC37L1 in open-access papers:
CDC37L1 is named in the same sentence as 7 diseases in open-access papers, as found by Europe PMC text mining. Sharing a sentence is not in itself a finding about the gene and the disease. The quoted sentences say what the papers report.
gastric cancer (3 papers, 2021 to 2025). A primary or metastatic malignant neoplasm involving the stomach. "The immunohistochemical staining of gastric cancer tissue microarrays revealed a marked decrease in CDC37L1 protein expression correlating with higher tumor grades in gastric cancer." (PMID 41369326, 2025). "Cell division cycle 37 like 1 (CDC37L1) is downregulated in gastric cancer and inhibits CDK6, as demonstrated from the experiments showcasing that Palbociclib inversed the effects of CDC37L1 silenced gastric cancer cells." (PMID 36769170, 2023). "Collectively, these findings identified CDC37L1 as a tumor suppressor in the development of gastric cancer." (PMID 33976724, 2021). "Therefore, our data identify CDC37L1 as a potential drug target for the treatment of gastric cancer." (PMID 33976724, 2021). "This study aimed to explore the expression and function of CDC37L1 in gastric cancer (GC)." (PMID 33976724, 2021). "In this study, we demonstrated for the first time that CDC37L1 plays an inhibiting role in proliferation and migration through down-regulating CDK6 expression in gastric cancer." (PMID 33976724, 2021).
heart failure (1 paper, 2024). Inability of the heart to pump blood at an adequate rate to meet tissue metabolic requirements. "Here, we report that CDC37L1 is significantly down-regulated in oHCM, compared with other heart failure aetiologies." (PMID 39200175, 2024).
schizophrenia (1 paper, 2025). A major psychotic disorder characterized by abnormalities in the perception or expression of reality. "Of the 10 potential candidate genes, 3 genes (Atad1, Cdc37l1, and Prkg1) were differentially expressed between schizophrenia patients and the control group." (PMID 41153356, 2025). "Finally, using an RNA-seq dataset, we found differential expression of ATAD1, including two other candidates, CDC37L1 and PRKG1, between schizophrenia and control groups, suggesting that examination of co-regulation of Atad1 and other “players” is warranted." (PMID 41153356, 2025).
tumor (4 papers, 2021 to 2025). "As expected, the results indicated that tumor size and weight derived from CDC37L1-silenced cells were remarkably smaller and lower in response to sorafenib, while no significant changes were observed between two groups without drug treatment." (PMID 35760798, 2022). "Therefore, unlike CDC37, which generally promotes oncogenic kinase activities and tumor development, CDC37L1 exhibits an opposing function by suppressing GC cell growth and motility through downregulating CDK6." (PMID 41369326, 2025). "These consequences demonstrated that CDC37L1 inhibits tumor growth in xenograft model of GC." (PMID 33976724, 2021). "Taken together, these findings unveiled a tumor-suppressive role of CDC37L1 in GC, and CDK6 may act as a downstream effector in this process." (PMID 33976724, 2021). "The results showed that overexpression of CDC37L1 effectively suppressed the tumorigenicity of BGC-823 cells, reduced the tumor size and weight comparing with control cells." (PMID 33976724, 2021). "However, no statistical difference was found between the expression of CDC37L1 or PPIA and the patients’ age, gender, grading, and tumor size and recurrence." (PMID 35760798, 2022).
cancer (1 paper, 2021). A tumor composed of atypical neoplastic, often pleomorphic cells that invade other tissues. "In order to explore the molecular mechanism via which CDC37L1 inhibited GC cell proliferation and migration, we detected the expression of several cancer signaling pathway factors, such as CDK4, CDK6, Cyclin D1, FAK, PI3K-P110 and mTOR through western blot assays." (PMID 33976724, 2021). "In addition to this, more functions of CDC37L1 in various kinds of cancers is waiting for exploiting." (PMID 33976724, 2021).
CDC37L1 also shares sentences with these, for which no sentence is quoted: hepatocellular carcinoma (2 papers); idiopathic dilated cardiomyopathy (1).